CCNA1 (cyclin A1)
Diseases named in the same sentence as CCNA1 in open-access papers (continued):
Sharing a sentence is not in itself a finding about the gene and the disease.
CCNA1 also shares sentences with these, for which no sentence is quoted: breast tumor (2 papers); multiple myeloma (2); rhabdomyosarcoma (2); Wilms tumor (2); adenocarcinoma (1); adrenocortical tumors (1); astrocytoma (1); bladder urothelial carcinomas (1); colon cancer (1); endothelial dysfunction (1); female infertility (1); follicular carcinoma (1); gastric adenocarcinoma (1); inflammatory breast carcinoma (1); Laron syndrome (1); lung adenocarcinoma (1); Myelodysplasia (1); nasopharyngeal carcinoma (1); osteosarcoma (1); pancreatic cancer (1); pituitary adenoma (1); skin carcinoma (1); squamous cervical cancer (1); testicular germ cell tumor (1); triple-negative breast carcinoma (1).